POTEKP (POTE ankyrin domain family member K, pseudogene)
Synonyms: FKSG30; POTE2delta; formerly ACTBL3; POTEK
Gene: Transcribed unprocessed pseudogene on chromosome 2 (131,591,752 to 131,628,147, forward strand). Ensembl gene ENSG00000204434.
Subcellular location: Cytoplasm, cytoskeleton
Diseases named in the same sentence as POTEKP in open-access papers:
POTEKP is named in the same sentence as 2 diseases in open-access papers, as found by Europe PMC text mining. Sharing a sentence is not in itself a finding about the gene and the disease. The quoted sentences say what the papers report.
lung carcinoma (1 paper, 2021). "TUBA1C, GAPDH, KRT25, GCC2, and POTEKP were the five proteins identified as potential lung cancer-specific exosome biomarkers." (PMID 34771645, 2021).
cancer (3 papers, 2018 to 2022). A tumor composed of atypical neoplastic, often pleomorphic cells that invade other tissues. "We identified 2 transcripts that were positively associated with LINC01087 expression in all 5 cancers: the pseudogene POTE ankyrin domain family member K (POTEKP) and the uncharacterized lncRNA AC093838.1." (PMID 36497462, 2022). "Such analysis identified 2 transcripts overlapping in the 5 cancer types, namely POTEKP and AC093838.1." (PMID 36497462, 2022).